MMP9 (matrix metallopeptidase 9)
Diseases named in the same sentence as MMP9 in open-access papers (continued):
Sharing a sentence is not in itself a finding about the gene and the disease.
Sciatica (2 papers, 2021). Pain in the lower back and hip radiating in the distribution of the sciatic nerve. "MMP9 is associated with sciatica in both peripheral blood and local discs." (PMID 33573686, 2021). "MMP9 is associated with sciatica in both the peripheral blood and local discs." (PMID 33535986, 2021). "Network analysis identified TLR4, MMP9, MPO, CAMP, RETN and TLR5 as key genes contributing to the dysregulation of genes in the peripheral blood of patients with sciatica." (PMID 33535986, 2021). "Combining these studies, a potential link between TLR4, MMP9, MPO, CAMP, RETN, and sciatica can be established, but microarray analysis showed that the expression of these genes was not changed after integrated TCM treatment." (PMID 33573686, 2021). "Consistent with the microarray data, the expression levels of the key genes (TLR4, MMP9, MPO, CAMP, RETN and TLR5) were significantly increased in patients with sciatica compared with healthy controls." (PMID 33535986, 2021). "The PPI network suggested that TLR4, MMP9, MPO, CAMP, RETN, TLR5, and IL1RN were key genes in the dysregulation of genes in the peripheral blood of patients with sciatica." (PMID 33573686, 2021). "Bioinformatic analysis revealed that most of the DEGs-baseline were related to immunity and the inflammatory response and that TLR4, MMP9, MPO, CAMP, RETN, TLR5, and IL1RN were key genes involved in the dysregulation of genes in the peripheral blood of patients with sciatica." (PMID 33573686, 2021).
scleritis (2 papers, 2022 to 2023). Inflammation of the sclera. "In addition, TNF-α elevates the level of MMPs, which may disrupt the balance between MMPs (MMP3 and MMP9) and TIMPs and induce scleritis." (PMID 35756002, 2022).
secondary progressive MS (2 papers, 2021 to 2024). "In patients with secondary progressive multiple sclerosis (MS), MMP-9 is expressed at the rim of plaques in chronic active lesions, suggestive for the expression of MMP-9 by activated microglia." (PMID 33498927, 2021). "In accordance with our results, clinical studies demonstrated a significant elevation in MMP-9 and MMP-2 serum levels in the RRMS, primary progressive form (PP-MS) and secondary progressive MS (SPMS) groups compared to healthy controls." (PMID 38438999, 2024).
Senile plaques (2 papers, 2012 to 2020). Senile plaques are extracellular deposits of amyloid in the gray matter of the brain. "However, an important consideration in assessing the potential efficacy of MMP9 in clearing amyloid deposits is that it is very difficult to know what concentration of enzyme would be required to clear senile plaques." (PMID 22496779, 2012). "In this study, we conducted a small preclinical investigation of whether NSCs could be modified to express metalloproteinase 9 (MMP9), a secreted protease reported to degrade aggregated Aβ peptides that are the major constituents of the senile plaques." (PMID 22496779, 2012).
serous carcinoma (2 papers, 2019 to 2023). "The immunoreactivity with MMP-9 increased gradually from secretory to hyperplastic endometrium and serous carcinoma (p < 0.05)." (PMID 36945954, 2023).
sickle cell anemia (2 papers, 2020 to 2021). "Similarly, RVX treatment decreased MCP-1 plasma levels and MMP-9 protein levels in the external jugular vein of mice following catheter thrombosis, as well as IL-6 plasma level and neutrophil levels in a mouse model of sickle cell disease." (PMID 33301454, 2020).
spinal cord ischemia (2 papers, 2014 to 2020). Reduced blood flow to the spinal cord which is supplied by the anterior spinal artery and the paired posterior spinal arteries. "The aim of this study is to investigate the roles of exogenous activation of CB2R on attenuating neurological deficit and blood-spinal cord barrier (BSCB) disruption during rat spinal cord ischemia reperfusion (I/R) injury, through modulation of the TLR4/MMP9 axis." (PMID 32248810, 2020).
spinal tuberculosis (2 papers, 2024). "MMP-9 is a central protein related to the immune system and is associated with immune cell infiltration in patients with spinal tuberculosis (STB)." (PMID 39712025, 2024).
Stillbirth (2 papers, 2011 to 2023). Death of the fetus in utero after at least 22 weeks of gestation. "Missense actin mutations in FLNB leading to atelosteogenesis type I and lethal skeletal dysplasia or inhibition of ERK/MMP-2 and MMP-9 pathways that are critical for trophoblast invasion, may be possible mechanisms of potentially lethal de novo FLNB SNVs in stillbirth etiology." (PMID 36800380, 2023).
synovial sarcoma (2 papers, 2013). "Synovial sarcoma showed inhibition of MMP-2 with TNF-α and slight stimulation of MMP-9 at 10 ng/ml." (PMID 24085323, 2013). "Synovial sarcoma was most sensitive to NM with block of MMP-2 at 500 μg/ml and MMP-9 at 100 μg/ml." (PMID 24085323, 2013).
teratoma (2 papers, 2017 to 2024). A non-seminomatous germ cell tumor characterized by the presence of various tissues which correspond to the different germinal layers (endoderm, mesoderm, and ectoderm). "We observed a significantly higher expression of Mmp9 in moderately and severely enlarged M19 tumor samples, too, indicating a similar role of MMP9 in teratomas." (PMID 39684459, 2024).
Thrombocytosis (2 papers, 2003 to 2021). Increased numbers of platelets in the peripheral blood. "Preoperative white cell count was associated with greater total MMP-9 (sum of pro- and active MMP-9, P=0.0006) and a trend towards a similar result was seen with thrombocytosis (P=0.06)." (PMID 12771921, 2003).
thyroid nodule (2 papers, 2018 to 2019). A small circumscribed mass in the THYROID GLAND that can be of neoplastic growth or non-neoplastic abnormality. "For further validation of MMP-9’s diagnostic value in the preoperative evaluation of thyroid nodules, analyzing the proposed gene in “intermediate” or “suspicious” FNA cases is required." (PMID 30509240, 2018).
thyrotoxicosis (2 papers, 2012 to 2013). A hypermetabolic syndrome caused by the elevation of thyroid hormone levels in the serum. "Radioiodine therapy of thyrotoxicosis does not alter serum MMP-2, MMP-9 or TIMP-1 concentrations either acutely or after about three months of observation." (PMID 23107223, 2012). "In summary, our study demonstrates that radioiodine treatment of thyrotoxicosis does not alter serum MMP-2, MMP-9 or TIMP-1 concentrations, either acutely or after about three months of observation." (PMID 23107223, 2012).
trigeminal neuralgia (2 papers, 2020 to 2025). Trigeminal neuralgia is a nerve disorder that causes a stabbing or electric-shock-like pain in parts of the face. "Taken together, these studies underline the central role of MMP-9 in the development of trigeminal neuralgia and provide a strong foundation for exploring new treatment options, with MMP-9 inhibition emerging as a particularly promising approach." (PMID 41245602, 2025). "For example, in trigeminal neuralgia, which is often caused by vascular compression, the inflammatory role of MMP-9 may be more relevant." (PMID 41245602, 2025). "This suggests that MMP-9, in particular, may play a crucial role in the onset and progression of trigeminal neuralgia." (PMID 41245602, 2025). "Similarly, resveratrol suppresses the proinflammatory cytokines IL-1β and TNF-α, inhibiting the activation of matrix metalloproteinase-9 (MMP-9) and MMP-2 by downregulation of the TLR-4-NF-κB signaling pathway in trigeminal neuralgia mice." (PMID 33014276, 2020).
tubulovillous adenoma (2 papers, 2012 to 2015). An epithelial neoplasm morphologically characterized by the presence of a villous and a tubular architectural pattern. "As found with IL-8, mean serum values of activated MMP-9 in patients with tubular or tubulovillous adenomas, as well as those at stage I adenocarcinoma, consistently remained within the control range." (PMID 22848630, 2012).
tularemia (2 papers, 2015 to 2016). Tularemia is an infection caused by the bacterium Francisella tularensis. "We previously demonstrated that overabundant lung infiltrating neutrophils are detrimental in tularemia as Mmp9-/- mice exhibited diminished leukocyte recruitment, reduced bacterial burden, and increased survival versus Wt mice." (PMID 27015566, 2016). "Others have demonstrated that excessive pulmonary MMP-9 activity can contribute to increased mortality during infection, with improved survival demonstrated in MMP-9 knockout mice compared to MMP-9+ littermates with respiratory tularemia." (PMID 26264019, 2015).
urolithiasis (2 papers, 2023 to 2025). Stone(s) within the urinary tract. "Also, MMP9 gene polymorphisms was also found to be related with urolithiasis." (PMID 37006258, 2023). "For LASSO regression analysis, six variables, MMP1, MMP3, MMP9, MMP10, MMP27 and, MMP28, were screened as diagnostic markers for urolithiasis." (PMID 37006258, 2023). "Matrix metalloproteinases, particularly MMP-9, are zinc-dependent endopeptidases involved in extracellular matrix (ECM) remodeling, inflammation, and kidney injury, all critical events in the pathophysiology of urolithiasis." (PMID 40573268, 2025). "Subsequently, we extracted DMMMPs and genes in urolithiasis-related modules for intersection and found MMP1, MMP3, MMP9, MMP12 were in the royalblue module and MMP10 were in the green module, suggesting all of DEMMPs might be implicated in RPs and urolithiasis." (PMID 37006258, 2023).
urothelial carcinoma (2 papers, 2021 to 2022). A malignant neoplasm derived from the transitional epithelium of the urinary tract (urinary bladder, ureter, urethra, or renal pelvis). "MMP-2 and MMP-9 are associated with epirubicin resistance in urothelial carcinoma (UC)." (PMID 34654351, 2021).
uterine fibroids (2 papers, 2022 to 2024). "Furthermore, miR-29 inhibitors promoted the protein expression of MMP-2 and MMP-9 (P < 0.01), and EMT promoting proteins N-cadherin, snail, vimentin, and Transwell assay showed that miR-29 inhibitors promoted cell migration in uterine leiomyoma (P < 0.01)." (PMID 35113040, 2022).
vascular malformation (2 papers, 2005 to 2013). A non-neoplastic disorder that is the result of defects of vascular morphogenesis. "Hyperstimulation of mouse brain with VEGF using adenoviral transduction causes an increase in capillary density, increased MMP-9 activity, and may, in the appropriate genetic background, result in small vascular malformations." (PMID 15667660, 2005).
venous thromboembolism (2 papers, 2023 to 2025). Occlusion of the lumen of a vein by a thrombus that has migrated from a distal site via the blood stream. "The levels of serum MMP-9 were increased by SP but interestingly, the levels of ADAMTS13 (e.g., the decreased level is marker of venous thromboembolism, VTE) was decreased by SP injection in hACE2 mice, when compared with untreated hACE2 mice." (PMID 38077924, 2023).
verrucous carcinoma (2 papers, 2015 to 2022). A well differentiated squamous cell carcinoma characterized by a papillary growth pattern, acanthosis, mild cytologic atypia, and pushing tumor margins.
viral meningitis (2 papers, 2004 to 2009). Inflammation of the membranes surrounding the brain and spinal cord due to a viral infection. "Other studies have reported strong correlations between MMP-9 and neutrophils in viral meningitis and with total white cells in TBM." (PMID 19789647, 2009).
vitreous hemorrhage (2 papers, 2017 to 2020). Blood extravasation in the vitreous humor. "Increased levels of pro-MMP-9 and activated MMP-9 have previously been found in the vitreous of patients with PDR associated with vitreous hemorrhage." (PMID 32962301, 2020).
actinomycetoma (1 paper, 2019). "Unlike IL-17A expression, we did found differences in MMP-9 expression between M. mycetomatis and the actinomycetoma lesions A. pelletierii and S. somaliensis." (PMID 31295246, 2019).
adenocarcinoma in situ (1 paper, 2022). A lesion in which the normally situated glands are partially or completely replaced by atypical cells with malignant characteristics. "In a clinicopathological study, the proportion of CAFs and MMP-9 levels increased gradually during the transformation of adenocarcinoma in situ into invasive adenocarcinoma, with CAFs being positively correlated with MMP-9 expression." (PMID 36422541, 2022).
adrenocortical tumors (1 paper, 2021). "Together, we showed that MMP-8 and MMP-9 play an important role in adrenocortical tumor cell motility, which may suggest a role in the metastatic process." (PMID 35201460, 2021).
alcohol abusers (1 paper, 2025). "Our results correlate with data from human studies, which show that MMP-9 levels are elevated in the serums of alcohol use disorder (AUD) patients." (PMID 39997037, 2025). "Moreover, chronic alcohol abusers were shown to have elevated serum MMP-9 concentrations." (PMID 39997037, 2025).
alcohol withdrawal (1 paper, 2025). "Patients experiencing alcohol withdrawal are distinguished by a reduced and more evenly distributed MMP-9 concentration." (PMID 39997037, 2025).
allergic conjunctivitis (1 paper, 2022). "On the contrary, MMP-9 was elevated, while the TIMP-1 levels were decreased in corneas with allergic conjunctivitis." (PMID 35692541, 2022).
alopecia (1 paper, 2023). Hair loss usually from the scalp. "Upregulation of MMP-9 is reported to be a major factor for hair follicle degeneration in alopecia." (PMID 36834812, 2023).
angiomyolipoma (1 paper, 2018). A neoplasm with perivascular epithelioid cell differentiation often associated with tuberous sclerosis. "Angiomyolipoma cells express mRNA coding for SDF-1α and 17-β-estradiol receptors and secrete both the metalloproteases principally involved in malignant phenotype acquisition, i.e. MMP-2 and MMP-9." (PMID 29920561, 2018).
anterior subcapsular cataracts (1 paper, 2022). "Further, in a mouse model of anterior subcapsular cataracts, MMP-9 played a significant role in mediating the epithelial-mesenchymal transition of LECs in anterior subcapsular cataracts." (PMID 35457074, 2022). "Rats with TGF-β-induced anterior subcapsular cataracts demonstrated elevated protein expression of MMP-2 and MMP-9 in lenses, and increased activity in conditioned medium from cultured lenses, indicating they may play a role in the formation of an ocular disorder." (PMID 35457074, 2022).
aortic valve calcification (1 paper, 2025). "Given that both aortic valve calcification and dilation present an inflammatory phenotype, MMP9 may also serve as a marker for the progression of valvular calcification." (PMID 41322480, 2025). "Combining bulk RNA-seq and scRNA-seq, it was found that MMP9 and PLAU are mainly related to the immune activation of monocytes and macrophages in aortic valve calcification, providing new insights for early AS treatment." (PMID 41322480, 2025).
asthenozoospermia (1 paper, 2018). "We determinedthe genotype distribution of C-1562T MMP-9 genepolymorphism in the three groups of fertile, asthenozoospermia,and terato-asthenozoospermia." (PMID 29043698, 2018).
autoimmune inner ear disease (1 paper, 2022). A syndrome characterized by rapidly progressive sensorineural hearing loss (SNHL), that is often bilateral, and is potentially reversible. "In addition, the balance of MMP9 and TIMP1 expression is thought to affect inflammation and corticosteroid response in patients suffering from autoimmune inner ear disease." (PMID 35573665, 2022).
autoimmune thyroiditis (1 paper, 2019). "In summary, our results suggest that decreased invasiveness of embryonic trophoblasts in autoimmune thyroiditis is associated with down-regulation of PD-1/PD-L1 signaling pathway and inhibition of MMP-2 and MMP-9 expression." (PMID 31656199, 2019). "Thus, we infer that, in the placenta of pregnant mice with autoimmune thyroiditis, attenuation of the PD-1/PD-L1 signaling pathway may inhibit p-ERK1/2 signaling and its downstream effects on MMP-2 and MMP-9." (PMID 31656199, 2019).
Bcc (1 paper, 2024). "Besides, patients with Bcc tended to show an increase in sputum MMP-9 and reduction in MMP-12 concentrations." (PMID 39011515, 2024).
Becker muscular dystrophy (1 paper, 2015). Becker muscular dystrophy (BMD) is a neuromuscular disease characterized by progressive muscle wasting and weakness due to degeneration of skeletal, smooth and cardiac muscle. "Our data suggest that serum levels of MMP-9, GDF-8 and FSTN are useful to discriminate DMD from controls (p < 0.05), to correlate with some neuromuscular assessments for DMD, and also to differentiate between Becker muscular dystrophy (BMD) and Limb-girdle muscular dystrophy (LGMD) patients." (PMID 26091074, 2015).
Behçet’s disease (1 paper, 2022). "Gelatinase B/MMP-9 rs17576 SNP was reported to have an association with many different diseases such as cancer, Henoch–Schonlein purpura, internal carotid artery bulb, and Behçet’s disease." (PMID 36138580, 2022).
benign adrenal tumors (1 paper, 2021). "In other study, serum MMP-9 levels were used as diagnostic tool in determining the functioning status of benign adrenal tumors." (PMID 35201460, 2021).
benign thyroid tumors (1 paper, 2019). "In a study of 66 patients with PTC and 40 patients with benign thyroid tumors, VEGF and MMP-9-positive expression were more frequently seen in PTC and were closely correlated to tumor size and clinical stage." (PMID 30704487, 2019).
Blindness (1 paper, 2021). Blindness is the condition of lacking visual perception defined as a profound reduction in visual perception. "Matrix metalloproteinases and in particular MMP9 are able to alter Bruch’s membrane integrity, thus potentially allowing neo-vessels responsible for blindness in neovascular AMD to reach the neural retina." (PMID 34544906, 2021).
bronchial carcinoma (1 paper, 2023). "Epidermal growth factor receptor (EGFR) and matrix-metalloproteinase 9 (MMP-9) are proteins linked to hyperproliferative diseases such as bronchial carcinoma and are associated with the formation of neointimal hyperplasia in numerous studies." (PMID 36867212, 2023).
brucellosis (1 paper, 2013). Brucellosis is a bacterial infection that spreads from animals to people via unpasteurized dairy products or by exposure to contaminated animal products or infected animals. "Interestingly, MMP-9 presence in CSF seems to be a feature of an active infection process in the CNS, since a patient who had brucellosis without neurological involvement did not display MMP-9 activity in its CSF sample." (PMID 23587438, 2013). "Interestingly, no MMP-9 activity was detected in the CSF sample from a patient suffering brucellosis without neurological involvement, in which neither anti-Brucella antibodies nor the bacterium were detected." (PMID 23587438, 2013).
buccal mucosa cancer (1 paper, 2013). "RT-PCR and western blot analyses were conducted to determine whether metastasis in the buccal mucosa cancer model was a result of gene regulation of metastatic mediators, specifically MMPs (MMP-2 and MMP-9) and TIMPs (TIMP-1 and TIMP-2)." (PMID 23599733, 2013).
campylobacteriosis (1 paper, 2018). Infections with bacteria of the genus campylobacter. "As Campylobacter infections are concerned, the data are scarce but some experimental studies have suggested MMPs, such as MMP-9, to have a role in campylobacteriosis in mice." (PMID 30551610, 2018). "In conclusion, after human Campylobacter enteritis, the serum levels of MMP-8, MMP-9 and their regulators MPO, HNE and TIMP-1 are elevated as compared to the serum levels of healthy controls." (PMID 30551610, 2018).